ALK (ALK receptor tyrosine kinase)
Diseases named in the same sentence as ALK in open-access papers (continued):
Sharing a sentence is not in itself a finding about the gene and the disease.
cancer (continued). "Understanding of the molecular event taking place during the development of the ALK‐positive NSCLC, and, in particular, identification of the EML4–ALK protein as a driver of this type of cancer, paved the way to develop targeted therapies." (PMID 41213866, 2025). "The prevalence of NTRK gene fusions is less than 1% across all cancers, and outside of non-small cell lung cancer, ALK gene fusions occur in about ∼ 0.2% of cancers." (PMID 39773366, 2025). "The integration of small-molecule ALK inhibitors has significantly advanced treatment options for ALK-positive cancers." (PMID 40422509, 2025). "By leveraging the comprehensive genomic and functional data presented here, a more precise and personalized approach to treating ALK-driven cancers can be developed, potentially improving patient outcomes in a wider range of malignancies." (PMID 40606598, 2025). "This idea is further supported by a recent assessment of ALK TKI-associated cardiotoxicity revealing that, in addition to the physiological burdens of cancer, old age and decreased cardiac function further increase the risk for drug-induced cardiac disorders." (PMID 40382638, 2025). "This work influences future preclinical and clinical investigations by providing a rationale to explore lorlatinib’s efficacy in a broader spectrum of ALK-driven cancers." (PMID 40606598, 2025). "Since translocations involving the ALK kinase are recurrent driver events in a range of human cancers, we initially focused on the development of models based on the NPM-ALK t(2:5) translocation." (PMID 40647524, 2025). "ALK is aberrantly expressed in cancer predominantly through gain-of-function alterations such as mutations or chromosomal translocations, and through high-level amplification in diverse childhood and adult cancers." (PMID 40813394, 2025). "This was often attributed to a lack of time during appointments, or HCPs’ unfamiliarity with their specific cancer subtype (most often ALK+)." (PMID 41149490, 2025). "The most frequently detected gene fusions using the automated RNA workflow involved ERG, FGFR2, and ALK, consistent with the prevalence reported for similar pan-cancer cohorts." (PMID 39674366, 2025). "This cancer type was selected due to its prevalence, the clinical importance of identifying ALK and ROS1 fusions for targeted therapy, and the need for rapid, cost-effective alternatives to traditional diagnostic methods such as FISH and IHC13–16." (PMID 40739404, 2025). "This pattern suggests that KRAS mutation carriers, who typically respond poorly to TKI intended for EGFR/ALK-positive cancers, often receive chemotherapy or radiation." (PMID 40502411, 2025). "In summary, ALK inhibitors have redefined the treatment paradigm of ALK-positive cancers and have provided a new dimension in the area of research and innovation." (PMID 40547482, 2025). "It remains to be established if there is an association with air pollutants and ALK‐positive NSCLC, and how those environmental factors can effect processes at the cellular and molecular levels to cause cancer." (PMID 41213866, 2025). "The integrated computational and experimental approach provides valuable insights for the rational design of optimized ALK inhibitors to address drug resistance in cancer therapy." (PMID 40872599, 2025). "The ALK‐positive NSCLC represents a unique cancer type with very distinct molecular and clinical‐pathological characteristics." (PMID 41213866, 2025). "These ALK fusions result in abnormal kinase activity, which drives cancer cell proliferation through pathways like RAS–ERK and PI3K‐AKT." (PMID 39810398, 2025). "With the rapid advancement and widespread application of next-generation DNA sequencing (NGS) technology, an increasing number of ALK fusion partners have been identified across various human cancers." (PMID 40054123, 2025).
cancer (continued). "Out of this series of 270 patients with a definitive diagnosis of cancer, molecular testing was carried out on 142 patients, looking for epidermal growth factor receptor (EGFR), anaplastic lymphoma kinase (ALK), c-ros oncogene 1 (ROS1) and PD-L1 mutations." (PMID 39941279, 2025). "ALK rearrangements occur at low prevalence in a spectrum of non-pulmonary solid tumors, yet they have emerged as actionable, pan-cancer driver events among solid neoplasms." (PMID 41246301, 2025). "In this study, we identified the anti-apoptotic MCL-1 adaptation in response to ALK inhibitors in cell lines and patient-derived cancer cells." (PMID 40113795, 2025). "The introduction of ALK inhibitors has dramatically changed the treatment paradigm for ALK-positive cancers." (PMID 40547482, 2025). "Variability in trial designs (e.g., combination therapies, line of treatment) and patient populations (e.g., EGFR/ALK status, cancer grading) further contributed to heterogeneity." (PMID 41000392, 2025). "Population-level genomic profiling identifies ALK alterations in ~3.3% of all cancers, with fusions/rearrangements representing a minority subset (~0.5%–0.8%)." (PMID 41246301, 2025). "Targeted therapies using tyrosine kinase inhibitors (TKIs) have shown efficacy against ALK-positive cancers, with crizotinib being the first TKI approved by the U.S. Food and Drug Administration (FDA) for NSCLC." (PMID 40606598, 2025). "Cytoplasmic ALK overexpression in high-grade serous ovarian cancer is correlated with a poorer prognosis, enhanced cancer stem cell features, enhanced migration, and proliferation." (PMID 40429950, 2025). "Several ongoing trials (NCT05770037, NCT04925609, and NCT05384626) continue to explore the broad applicability of ALK inhibitors across different cancer types, focusing on treatment resistance, brain metastases, and CNS-related side effects." (PMID 40576713, 2025). "We discovered that two cancer-driving proteins, ALK and SRC, directly modify and activate a key metabolic enzyme called IMPDH2." (PMID 41154443, 2025). "Emerging research implicates breast cancer gene 1 and 2 (BRCA1/2) mutations and anaplastic lymphoma kinase (ALK) fusions in pathogenesis." (PMID 41246574, 2025). "Nevertheless, the binding energies to lorlatinib suggest that lorlatinib remains effective against all 53 ALK amino acid substitutions classified as deleterious or damaging in cancer." (PMID 40606598, 2025). "Second-generation ALK inhibitors, including ceritinib, alectinib, and brigatinib, have been developed to treat cancer patients who have experienced crizotinib resistance." (PMID 40346640, 2025). "ALK-rearranged carcinomas are less frequent than those with RET or NTRK rearrangements, and typically involve fusion with partner genes, such as STRN (encoding striatin) or EML4 (also involved in lung adenocarcinoma)." (PMID 41175860, 2025). "Some ALK-rearranged carcinomas display the features of diffuse sclerosing papillary carcinoma, others have poorly differentiated morphology." (PMID 41175860, 2025). "The discovery of rearrangements in the ALK gene and ALK tyrosine kinase inhibitors has resulted in a dramatic improvement in the prognosis of patients with this subtype of cancer." (PMID 39457620, 2024). "The two most common variants, variant 1 (V1) and variant 3 (V3), collectively account for approximately 80% of ALK+ cancers." (PMID 38458397, 2024). "Comparatively, TOPK emerges as a superior target for cancer therapy compared to other direct downstream molecules of ALK, including Smad4, STAT3, PI3K, and PLC-γ." (PMID 38397899, 2024). "Anaplastic lymphoma kinase (ALK), belonging to the insulin receptor superfamily, plays a significant role in various cancers." (PMID 38397899, 2024). "EGFR signaling promotes survival and resistance to ALK inhibitors in EML4-ALK+ cancer cells in vitro, in animal studies, and in patients." (PMID 39488530, 2024).
cancer (continued). "Age was included as a covariate for apparent clearance (CL/F), while prior anti-cancer therapy in ALK+ patients (ALKPOT) was included for apparent volume of distribution (V/F)." (PMID 39081957, 2024). "As ALK or ROS1 fusion proteins are mainly expressed in cancer cells, we mainly focused on MET kinase." (PMID 37733896, 2024). "Anaplastic Lymphoma Kinase (ALK) inhibitors have revolutionized the treatment of ALK-positive cancers, particularly non-small cell lung cancer (NSCLC)." (PMID 38339401, 2024). "Patients with ALK-positive cancer (median [IQR] age, 55 years) were younger than patients with EGFR-positive (median [IQR] age, 62 years) and WT (median [IQR] age, 64 years) cancer." (PMID 38334998, 2024). "Changes in the structure of the ALK gene significantly contribute to the onset of different human cancers, and therapies aimed at this gene have revolutionized how we treat these tumors driven by this specific oncogene." (PMID 38397899, 2024). "The most prominent alterations involved the ALK RTK, which is affected by oncogenic translocations or point mutations in various cancers." (PMID 38168093, 2024). "Using the Cancer Genome Interpreter, we identified five recurrent cancer driver mutations spanning MUC16, MUC4, ALK, and CTNND1, with the latter being novel and containing a missense mutation, R439C." (PMID 39338204, 2024). "In ALK-positive cancers treated with crizotinib, progression in the central nervous system is common, which is due to the low concentration of the drug in the cerebrospinal fluid." (PMID 39457620, 2024). "Crizotinib is a potent ATP-competitive ALK inhibitor with demonstrated activity against ALK-related cancers, such as ALCL and NSCLC." (PMID 39703852, 2024). "It is believed that alectinib works by blocking the activity of the ALK protein, thus inhibiting the proliferation of cancer cells and promoting their death." (PMID 39766122, 2024). "The treatment of choice for oligoprogression of ALK-positive cancer is local treatment with radiotherapy and maintenance of current systemic therapy." (PMID 39457620, 2024). "They ligated folate to three PROTAC molecules (ARV-771, MS432, and MS99) to degrade BRDs, MEKs, and ALK in cancer cells, respectively." (PMID 38582446, 2024). "TCE and CAR Ts are able to take effect both on ALK transgenic 293T cells (293T-ALK) and cancer cells that intrinsically express ALK." (PMID 38804307, 2024). "These mutations lead to the abnormal activation of the ALK protein, which promotes cancer cell survival and proliferation, making ALK inhibitors an effective treatment in targeted cancer therapies." (PMID 39684787, 2024). "Anaplastic lymphoma kinase (ALK) plays a role in the development of the nervous system and is implicated in various cancers." (PMID 39138146, 2024). "Lorlatinib is an ALK inhibitor with good brain tissue penetration, effective in treating cancers having increased drive by ALK overexpression or overactivity." (PMID 39056757, 2024). "ALK-specific TKIs (crizotinib, alectinib, or lorlatinib) also impaired the growth of the cancer cells as single agents, but a substantial number of persister cells remained in culture." (PMID 38483480, 2024). "ALK TKIs have the potential to inhibit ALK phosphorylation and downstream signalling, leading to cell cycle arrest in the G1-S phase and apoptosis of cancer cells." (PMID 37940761, 2024). "ERBB3 overexpression occurs in several cancers and has a central role in the development of drug-resistance to several tyrosine kinase inhibitors including ALK-TKI." (PMID 39695132, 2024). "The ALK locus is subject to chromosomal translocations and inversions that give rise to >25 oncogenic fusion proteins in a number of different cancers." (PMID 38713862, 2024). "YAP1 has been shown to mediate survival in cancer cells that harbor the ALK rearrangement when they are treated with alectinib." (PMID 38835344, 2024).
cancer (continued). "ALK rearrangements are genomic alterations that play a critical role in cancer development and progression." (PMID 39851929, 2024). "A significant contributor to NSCLC oncogenesis is the mesenchymal lymphoma kinase (anaplastic lymphoma receptor tyrosine kinase [ALK]) fusion mutations, often associated with accelerated cancer progression." (PMID 38481812, 2024). "Concomitantly upregulated Hedgehog signaling (Hh) in ALK positive cancers can complicate treatment with any ALK inhibitor." (PMID 39056757, 2024). "The role of STAT3 inhibitors in treating SQSTM1-ALK fusion-positive cancers, as well as the combination of ALK and STAT3 inhibitors, warrants further investigation." (PMID 39555099, 2024). "ALK is primarily known for its oncogenic role in several human cancers, and it is a therapeutic target for ALK-altered cancers." (PMID 38307859, 2024). "Mutations in the ALK gene can result in its oncogenic activation, with the resulting cancers classified as ALK-positive." (PMID 39728071, 2024). "Key targeted therapies include RET inhibitors like selpercatinib for RET rearrangements, ALK inhibitors like alectinib and crizotinib for ALK gene alterations, and EGFR inhibitors like osimertinib and erlotinib for EGFR-mutated cancers." (PMID 39457373, 2024). "ALK inhibitors exemplify the breakthroughs in patient prognosis that have been made over the years by personalizing the treatment of cancer patients and breaking through resistance mechanisms that contributed to early treatment failure." (PMID 39457620, 2024). "Several antibodies that bind to the ALK extracellular domain showed inhibition of cancer cell growth in vitro and in vivo." (PMID 38804307, 2024). "Taken together, FACTS demonstrated functional fusion oncogene formation through genome-wide translocations after a single DSB at ALK intron 19 and reproduced ALK fusion landscape in human cancers." (PMID 38877018, 2024). "(R)-crizotinib is clinically used to inhibit ALK kinase in specific cancers and is our focus in the current review." (PMID 39001541, 2024). "Meanwhile, MTOR was found to be linked to PIK3C; BRAF and MAPK1 were found to be linked to EGFR; and ERBB2 and ALK are linked to the common NSCLC and Cancer pathway." (PMID 38921583, 2024). "For EML4-ALK+ cancers, reactivation of RTKs after ALK inhibition similarly promotes drug tolerance and acquired resistance, although the mechanisms of reactivation are not well understood." (PMID 39488530, 2024). "In summary, we hope that the current approach can be seen as an important new direction in RNA-based molecular cancer diagnostics for ALK and other oncogenic genome rearrangements." (PMID 39594806, 2024). "In this work, we provided preclinical evidence supporting the efficacy of combining TKIs with anti-CD47 mAb in both blood and solid ALK-positive cancers." (PMID 39767726, 2024). "ALK inhibitors are the standard treatment for ALK+ cancers with first-, second- and third-generation inhibitors already in the clinic." (PMID 39682703, 2024). "These advancements are tailored to attack specific cancer cells based on genetic markers, such as mutations in the epidermal growth factor receptor (EGFR), anaplastic lymphoma kinase (ALK), and c-ros oncogene 1 (ROS1) genes." (PMID 39044884, 2024). "ALK translocations are prevalent in various cancers, primarily resulting in the constitutive activation of ALK kinase activity." (PMID 39703852, 2024). "ALK-driven cancers comprise a panel of blood and solid malignancies that are associated with a dismal prognosis, particularly in the relapsed/refractory setting." (PMID 39767726, 2024). "Gilteritinib effectively counteracts the development of resistance to lorlatinib in cancer cases with ALK rearrangements." (PMID 38655260, 2024). "Most of these cancers exhibit a biologically simple cancer network, often characterized by a single predominant oncogenic driver, such as an EGFR or ALK mutation." (PMID 39300154, 2024).
cancer (continued). "These drugs specifically target the ALK protein, thereby inhibiting the cancer growth and survival pathways." (PMID 39851929, 2024). "Accordingly, abnormal regulation of genetic factors, such as NF-κB, MYCN, ALK, and Nrf2, has been constantly and similarly observed in various cancer types." (PMID 38666930, 2024). "Targeting ALK through RNA interference, monoclonal antibodies, small molecule inhibitors, has benefited patients in personalized cancer treatment." (PMID 38403820, 2024). "Dual inhibition of ALK and ERBB receptors or AKT disrupts RAS/MAPK and AKT/PI3K signalling pathways, and enhances apoptosis in EML4-ALK + NSCLC cancer cells." (PMID 39695132, 2024). "The levels of several mRNAs that code for surface proteins with roles in cancer were similarly upregulated, including ALK, PTPRM, PTPRF, PTPRK, and SVEP1." (PMID 39335212, 2024). "Activation of ALK signaling in a cancer cell can occur through gene fusion, amplification or point-activating mutation." (PMID 39457620, 2024). "In the process of oncogenesis, the ALK gene translocates with another partner gene, leading to a fusion oncogene that overexpresses in cancers." (PMID 38655260, 2024). "Prominent examples of targeted inhibitors used as first-line treatment in NSCLC are Osimertinib and Alectinib for advanced EGFR-mutant or ALK fusion-positive cancers, respectively." (PMID 38702301, 2024). "There was a significant enrichment of YAP-associated transcripts in DTPs across EGFR-mutant, ALK fusion-positive, and KRAS-mutant cancer cell." (PMID 38702301, 2024). "Crizotinib, which is approved for the treatment of ALK- and ROS1-driven carcinomas, was historically developed as a MET inhibitor and, expectedly, demonstrated clinical activity towards MET-mutated carcinomas." (PMID 38966170, 2024). "mRNA expression of HER3 in ALK-translocated cancers was similar to that in the wild type, while the median protein expression of HER3 was higher; however, the difference was not statistically significant." (PMID 37722715, 2023). "Targeted therapies, such as ALK inhibitors, have been developed to specifically target the ALK fusion protein and inhibit its activity, which can slow or stop the growth of cancer cells." (PMID 37901797, 2023). "This analysis revealed activation of kinases routinely associated with other RTKs (e.g., ALK, EGFR, RET) in cancer." (PMID 37587872, 2023). "Upregulation of CTCFL is required for resistance to ALK inhibition in cancer cells via promoting chromatin interactions." (PMID 37120564, 2023). "Entrectinib, with similar potency, inhibits anaplastic lymphoma kinase (ALK), ROS1 and tropomyosin receptor kinase (TRK), showing antiproliferative activity in cancers originating from gene fusion mutations involving these proteins." (PMID 38202651, 2023). "Anaplastic lymphoma kinase (ALK) gene alterations are gaining more attention as pan-cancer markers in both solid and hematological malignancies." (PMID 37773318, 2023). "This is because SHP2 is expressed ubiquitously, but ALK expression is largely restricted to cancer cells." (PMID 37339995, 2023). "Ceritinib has been tested in clinical trials, and shown efficacy in malignant tumors with ALK rearrangement." (PMID 36809604, 2023). "A clinical study has demonstrated that cancer cells carrying an ALK rearrangement (ALK-positive) are sensitive to ALK inhibition." (PMID 38074113, 2023). "contributes to the mounting evidence that ALK is an immunogenic oncoprotein and bolsters the argument that an ALK cancer vaccine is needed to prime the immune system for effective immunotherapy in ALK+ NSCLC patients." (PMID 37795653, 2023). "The remaining most frequent mutated cancer driver genes found in early-stage samples (KMT2C, ALK, BRCA2, GRM, ATM, and BRCA1) were not among those found to be the most frequently shared in late-stage samples (MUC16, CSMD3, KNT2C, NF1, LRP1B, SPEN, and TRRAP)." (PMID 37446001, 2023).